RN7SL306P (RNA, 7SL, cytoplasmic 306, pseudogene)
Gene: Miscellaneous RNA gene on chromosome 7 (128,970,734 to 128,971,029, forward strand). Ensembl gene ENSG00000242241.
Homologues: Orthologues: chimpanzee Metazoa_SRP (97% identical). Paralogues in human: RN7SL2 (76% identical), RN7SL1 (75% identical), RN7SL3 (73% identical), RN7SL606P (73% identical), RN7SL126P (73% identical), RN7SL311P (73% identical), RN7SL479P (73% identical), RN7SL575P (73% identical), RN7SL743P (73% identical), RN7SL7P (73% identical), RN7SL45P (73% identical), RN7SL680P (72% identical), and 703 more.